CD4 (CD4 molecule)
Diseases named in the same sentence as CD4 in open-access papers (continued):
Sharing a sentence is not in itself a finding about the gene and the disease.
glioblastoma (continued). "The GAPVAC-101 trial investigated the combination of a warehouse vaccine and a fully personalized vaccine in glioblastoma patients and showed the induction of both CD8+ and CD4+ T cell responses." (PMID 35464395, 2022). "Similar to CD4+ T cells, there was enrichment of CCR2+CD8+ Tcm cells in glioblastoma compared to paired blood samples, and approximately 50% of CD8+ glioblastoma Trms expressed CCR2." (PMID 35464424, 2022). "Remarkably, PD-1 expression was significantly decreased on CD4+ and CD8+ T cells in the TIME of all indications, except glioblastoma." (PMID 35464481, 2022). "T-cell subsets that participate in anti-tumour immunity, including CD4+ and CD8+ memory subsets and T regulatory cells (Tregs), have been identified in glioblastoma." (PMID 35464424, 2022). "Of note, significantly fewer naïve CD4+ and CD8+ T cells were detected in glioblastoma biopsies compared to paired blood samples, indicating limited blood contamination of these resected glioblastoma biopsies obtained at surgery." (PMID 35464424, 2022). "Lastly, CX3CR1 expression was low among all CD4+ T-cell subsets except CD4+ Temra cells, where CX3CR1 expression was enriched in the blood and significantly lower in glioblastoma." (PMID 35464424, 2022). "Accordingly, the greatest frequency of CD49a+ cells identified here were the Trm populations, yet moderate proportions of multiple CD4+ and CD8+ T-cell subsets expressed CD49a and were enriched in glioblastoma." (PMID 35464424, 2022). "CXCR6, a marker of Trm cells, was indeed expressed by a high proportion of both CD4+ and CD8+ Trm cells in glioblastoma." (PMID 35464424, 2022). "treated glioblastoma patients with an individualized multi-epitope vaccine (NCT02287428), leading to increased neoantigen-specific CD4+ and CD8+ T cells responses in peripheral blood." (PMID 34513673, 2021). "There was a significant difference in tumour RFI between chemoradiotherapy and radiotherapy (p = 0.030) in glioblastoma cases with a high expression of CD204+TAMs and a low expression of CD4+TILs." (PMID 35201470, 2021). "A study showed that glioblastoma-released sEVs expressing PD-L1 inhibited the activation and proliferation of CD4+ T and CD8+ T cells by binding to PD-1, leading to immune escape of glioblastoma cells." (PMID 34094979, 2021). "We investigated paired human glioblastoma samples from primary and subsequent progressive disease for the presence of CSF1R, CD204, CD163, PD1, PD-L1, CD3, CD4, and CD8." (PMID 34063518, 2021). "The success of CD4 T cell ACT also arises from the use of CD4 CAR T cells, in particular in glioblastoma and leukemic patients." (PMID 34064410, 2021). "A large number of CD4+ T cells, CD8+ T cells, and NK cells including WT1-specific CD8+ and CD4+ T cells infiltrated into the glioblastoma in WT1 peptide vaccine-treated mice." (PMID 34355173, 2021). "Thirteen cases of matched primary and recurrent glioblastoma tissue were immunohistochemically labelled for CD3, CD8, CD4 and PD-1, and TIL density assessed." (PMID 34676050, 2021). "Subsequent immune infiltration analysis showed that CD96 was positively correlated with infiltrating levels of CD4 + T and CD8 + T cells, macrophages, neutrophils, and DCs in glioblastoma multiforme and low-grade glioma." (PMID 32695752, 2020). "Neoantigen-based vaccines showed promising results in terms of neoantigen-specific CD4 and CD8 T cell responses and survival in both melanoma and glioblastoma, suggesting a potential benefit in other cancers including CRC." (PMID 32210966, 2020). "While CD4+ Tregs have been under extensive investigation for decades, the existence and role of CD8+ Tregs is less well studied and is not well understood in glioblastoma." (PMID 30568917, 2018). "CD4+/PD1+ TILs were dysfunctional in the presence of PD-L1 among patients with head and neck squamous cell carcinomas and glioblastoma multiforme (GBM)." (PMID 30069490, 2018).
glioblastoma (continued). "For example, compared to healthy controls, patients with glioblastoma multiform exhibit lower percentages of total T cells, an accumulation of γδ T cells, and expansions of αβ T cells with CD4+CD28− and CD4+CD57+ phenotypes." (PMID 28751932, 2017). "While PD-1 expression has been widely investigated, its role in CD4+ effector T cells in the setting of health and cancer remains unclear, particularly in the setting of glioblastoma multiforme (GBM), the most aggressive and common form of brain cancer." (PMID 28880903, 2017). "Similarly, previous preclinical investigations have shown that checkpoint blockade combined with PD-1 and BTLA can exert synergistic antitumor effects by directly activating CD4+ and CD8+ T cells in glioblastoma." (PMID 40463377, 2025). "However, healthy donor CD4+ and CD8+ T cells stimulated with phorbol 12-myristate 13-acetate (PMA) and ionomycin had a significantly lower percentage of TIM-3 positivity compared to stimulated CD4+ and CD8+ T cells from glioblastoma patients." (PMID 40072074, 2025). "However, we saw a significant reduction in the percentage of CD69 and IFNγ positivity in PMA and ionomycin-stimulated CD4+ and CD8+ T cells and NK cells from glioblastoma patients compared to their counterparts in healthy donors." (PMID 40072074, 2025). "However, they did observe an increase in percentage of TIM-3 positivity on tumor-infiltrating CD4+ and CD8+ T cells compared to peripheral CD4+ and CD8+ T cells from both primary and recurrent glioblastoma patients." (PMID 40072074, 2025). "In addition, glioblastoma and RRMS patients shared higher fractions of KLRG1+ CD4+ TTE, whereas CD8+ effector and memory Tc were only elevated in RRMS patients compared to controls." (PMID 39497174, 2024). "Similarly, the low abundance of CD4+ and CD8+ T cells and NK cells in the overall PBMC population from glioblastoma patients and, hence, the very low abundance of extracted RNA from these isolated populations prevented us from confirming flow results by qPCR." (PMID 39513882, 2024). "As TIM-3 is associated with reduced T cell effector function, and as we observed changes in the percentage of TIM-3 positivity on CD4+ and CD8+ T cells and NK cells from glioblastoma patients, we next evaluated the activation statuses of these T cell subsets and NK cells." (PMID 39513882, 2024). "However, a significantly reduced level of induction of CD69 percentage positivity was seen on stimulated CD4+ and CD8+ T cells and NK cells from glioblastoma patients compared to healthy donors." (PMID 39513882, 2024). "A subsequent analysis of molecules known to co-ordinate TIM-3 function and regulation was performed, which revealed that BAT3 expression was significantly reduced in CD4+ and CD8+ T cells, as well as NK cells from glioblastoma patients compared to counterparts from healthy donors." (PMID 39513882, 2024). "However, a significantly reduced level of induction of IFNγ positivity was seen on stimulated CD4+ and CD8+ T cells and NK cells from glioblastoma patients." (PMID 39513882, 2024). "Glioblastoma multiforme (GBM) is a typical immunosuppressive tumor characterized by T‐cell exhaustion, with low levels of CD8+ T cells and a limited response from the remaining CD4+ T cells against antigen attack." (PMID 39713200, 2024). "The observed inverse correlation between SQLE mRNA and CD4+ T‐cell infiltration, coupled with improved outcomes of SQLE inhibition alongside immune checkpoint blockades in glioblastoma, suggests a need to scrutinize the effects of SQLE and FR194738 on OSA's immune response." (PMID 38372422, 2024). "Furthermore, Th17 (Tc-II 15) were higher and Th9 (Tc-II 7), CD4+ naïve Tc (Tc-I 8), and KLRG1+CD4−CD8− Tc (DN Tc) (Tc-I 30) were lower in glioblastoma in comparison to controls." (PMID 39497174, 2024).
glioblastoma (continued). "Comparable to glioblastoma patients, RRMS patients had higher fractions of KLRG1+CD4+ TTE (Tc-I 25) and reduced percentages of KLRG1+CD4+ TTM (Tc-I 6), KLRG1+CD4+ TCM (Tc-I 3), CD4+ TEM (Tc-I 11), and Th9 (Tc-II 7) compared to controls." (PMID 39497174, 2024). "Such additional work may generate more nuanced knowledge of the glioblastoma TME and the interactions between anti-inflammatory TAMs, CD4+/CD8+ T cells and immune suppression, and is likely to yield novel therapeutic targets." (PMID 37324244, 2023). "We showed glioblastoma invasive margins have a different immune profile compared with the core, including reduced TAM motility/activation (Iba1, CD68), increased homeostatic microglia (P2RY12) and reduced CD4+ T and NK cells." (PMID 37324244, 2023). "The immune cell infiltrate of seven primary glioblastomas and two spinal metastases from seven patients with rare POLE variants as determined by multiplexed fluorescence IHC of immune cell markers CD3, CD4, CD8, CD68, and PD-1 was compared to that in POLE WT glioblastomas." (PMID 37990341, 2023). "The primary glioblastoma of patient Fam011-III.1/M1 showed an increased immune infiltrate compared to a POLE WT glioblastoma, which was composed mainly of PD-1-positive CD3+ T lymphocytes co-expressing CD4, and CD68+ macrophages." (PMID 37990341, 2023). "We first examined the glioblastoma immunopeptidomes of 19 patients for HLA class II-bound bacterial peptides, and next whether TILs and TIL-derived CD4+ T cell clones (TCCs) in one of the patients react against HLA-bound bacterial peptides and tumour antigens." (PMID 37198490, 2023). "In addition, the enzymatic removal of sialic acids in glioblastoma-derived EVs led to their enhanced EV uptake by dendritic cells also in a DC-SIGN dependent manner, and the activation of both CD8+ and CD4+ T cell responses." (PMID 36430846, 2022). "Similarly, we observed a decrease in the proportion of CX3CR1+CD4+ Temra and CX3CR1+CD8+ Tem and Temra subsets in glioblastoma compared to paired blood samples, suggesting little requirement for CX3CR1 in glioblastoma infiltration." (PMID 35464424, 2022). "However, CXCR4-blockade in combination with anti-PD-1 has been shown to have a synergistic effect in increasing the proportion of IFNγ+ and TNFα+ producing CD4+ and CD8+ T cells in the brains of mice with glioblastoma." (PMID 35464424, 2022). "The activation- and exhaustion-specific markers of Tregs and activated CD4+ and CD8+ T cells have been investigated in glioblastoma but the migratory receptors required by these subsets for glioblastoma-homing remain unknown." (PMID 35464424, 2022). "The reduction of tumor cell proliferation by CD3+, CD4+, and CD8+ T3 cells could increase the survival rate and reduce tumor development in mice with glioblastoma." (PMID 36146527, 2022). "Our results revealed that STAT3 expression was positively correlated with infiltration of macrophages, dendritic cells, CD4+ T cells, CD8+ T cells, neutrophils, and B cells (all r > 0.06, p < 0.005) in all cancer types analyzed, with the exception of glioblastoma multiforme (GBM)." (PMID 33668805, 2021). "However, this response differed across tumor types, with IL-12 resulting in largely CD4 migration in fibrosarcoma but pre-dominantly CD8 migration in ovarian cancer, and further work is required to determine its impact in glioblastoma." (PMID 34771532, 2021). "Additionally, exosomes from human glioblastoma culture block both CD8+ and CD4+ T cell proliferation." (PMID 33178688, 2020). "MDMs and activated CD4+ T cells, both obtained from multiple donors, dividing and PMA-treated (differentiated) THP-1 and U937 cells, as well as U87-MG glioblastoma cells, were treated with 1000 U/ml IFNα for 24 h (for detailed description of experimental procedures)." (PMID 23442224, 2013). "However, the stimulation of CD4+ T, CD8+ T, and NK cells from glioblastoma patients did not cause any change in BAT3 positivity." (PMID 39513882, 2024).
glioblastoma (continued). "With multiple antigen epitopes for patients with glioblastoma, neoantigen-specific CD4+ and CD8+ T cells from the peripheral blood could infiltrate into intracranial glioblastoma in patients, paving a new avenue for immunotherapy targeting glioblastoma TME." (PMID 38685033, 2024). "Furthermore, in-depth phenotyping of PB immune cells also revealed changes in the effector and memory Tc compartment with similarities in KLRG1+ CD4+ TTE between RRMS and glioblastoma patients and differences in CD8+ effector and memory Tc and activated CD4+ TSCM." (PMID 39497174, 2024). "Indeed, TIM-3 expression is regarded as a marker for terminally differentiated effector and exhausted cells, thereby suggesting that CD4+ and CD8+ T cells and NK cells may be terminally exhausted in glioblastoma patients." (PMID 39513882, 2024). "GL261-CIITA cells are a potent anti-glioblastoma vaccine, stimulating a protective adaptive anti-tumor immune response in vivo as a consequence of CIITA-driven MHC class II expression and consequent acquisition of surrogate antigen-presenting function toward tumor-specific CD4+ Th cells." (PMID 36993983, 2023). "In an independent large glioblastoma cohort with transcriptomic data, positive correlations between anti-inflammatory microglia/macrophage markers (triggering receptor expressed on myeloid cells 2, CD163 and CD32a) and CD4+/CD8+/programmed death-ligand 1 RNA expression were validated (P < 0.001)." (PMID 37324244, 2023). "Additionally, CD4+ CAR T cells showed persistent tumor challenge and effective function, whereas CD8+ CAR T cells were exhausted immediately after expressing their effective function following stimulation with IL13Rα2+ glioblastoma (GBM) cells." (PMID 38328405, 2023). "However, CCL19 may also promote the migration of regulatory T cells (CD4+CD25+FoxP3+) and therefore its usefulness in glioblastoma is unclear." (PMID 34771532, 2021). "In a study with healthy subjects and glioblastoma multiforme (GBM) patients, PD1+ CD4+ T cells were found to be unable to proliferate but secrete IFN-γ and display exhaustion markers in RNA sequencing analyses." (PMID 34012451, 2021). "Indeed, immune cells isolated from peripheral blood of patients with glioblastoma exhibit more CD4+/CD25+/FOXP3+ Treg cells relative to those of patients without glioblastoma." (PMID 33396284, 2020). "However, Tregs are found in the blood of glioblastoma patients at a higher ratio to CD4+ non-Tregs as compared to healthy controls." (PMID 30568917, 2018). "However, in the context of human glioblastoma, immune function of local APC may be compromised, and the full potential of CD4 T cells functioning in the tumour bed may thus require concomitant modulation of the tumour microenvironment." (PMID 23717511, 2013). "For example, studies have found that Zika virus (ZIKV) could induce strong pro-inflammatory responses and increase CD4+ and CD8+ T-cell tumor infiltration and activation in a mouse model of Glioblastoma Multiforme (GBM)." (PMID 38005401, 2023). "Further, CD4+ T cells have been shown to help alleviate exhaustion of CD8+ T cells during chronic infection, and CD4+ T cells have been shown to have longer persistence and better potency in glioblastoma, so AAK1ΔN125 expression in these settings could be desirable." (PMID 38143765, 2023). "Interestingly, epithelioid glioblastoma cells express MHC class II antigen, CD68, and colony-stimulating factor receptor-1 commonly found in microglia/macrophage lineage, and therefore, they may interact with CD4+ and NK cells in the process." (PMID 36703629, 2022). "In addition, both studies targeting glioblastoma epitopes showed that mutant peptide epitopes favored expansion of cytotoxic CD4+ T-cells and even if peptides were used to target CD8+ T-cells, peptide antigen-specific CD4+ T-cell expansion was observed in both studies." (PMID 34335558, 2021).
glioblastoma (continued). "We recently observed similar findings where percentage of TIM-3 positivity on peripheral T cells (CD4+, CD8+, and Tregs) from glioblastoma patients were not significantly different to that seen on peripheral counterparts from age-matched healthy individuals." (PMID 40072074, 2025). "The human glioblastoma-astrocytoma cell line U373-MAGI was derived from a malignant brain tumor and expresses CD4 but not CCR5, and only minimal amounts of CXCR455." (PMID 39827271, 2025). "We observed similar results to others where the percentage of TIM-3 positivity was not significantly different on unstimulated CD4+ and CD8+ T cells and NK cells from healthy donors and glioblastoma patients." (PMID 40072074, 2025). "Cell surface TIM-3, but not ENTPD1, was also elevated on activated CD4+ and CD8+ T cells, as well as on NK cells from glioblastoma patients compared to healthy donor T and NK cells." (PMID 39513882, 2024). "Unlike CD4+ and CD8+ T cells and NK cells from healthy donors, stimulation did not enhance the percentage positivity of BAT3 in CD4+ and CD8+ T cells or NK cells from glioblastoma patients." (PMID 39513882, 2024). "Equally high proportions of CD4+ T-cell subsets in both blood and glioblastoma expressed CXCR4, hence no enrichment of this receptor was observed in glioblastoma." (PMID 35464424, 2022). "In an in vivo model of glioblastoma multiforme, human CMV/HSV-1 oncolytic virotherapy elicited an immune response characterized by the significant induction of CD8+ T cells, but not CD4+ T cells." (PMID 33668202, 2021). "Surprisingly, CD40L expression was also detected in non-lymphocyte-infiltrated glioblastomas, hinting at CD40L cellular source other than CD4+ T cells." (PMID 29244745, 2017). "In this study, no treatment-induced immunosuppression as assessed by DTH, CD4, CD8, immunoglobulin, and complement levels was observed, an important consideration, given the immunosuppression frequently observed in glioblastoma patients, both due to their disease and treatment." (PMID 38216554, 2024).